CALD1 (caldesmon 1)
Diseases named in the same sentence as CALD1 in open-access papers (continued):
Sharing a sentence is not in itself a finding about the gene and the disease.
colorectal cancer (8 papers, 2018 to 2024). A primary or metastatic malignant neoplasm that affects the colon or rectum. "The seven significant colorectal cancer associated genes shortlisted from the differentially expressed genes were CALD1, CTNNB1, CXCL14, PTCH1, CXCL8, TNFAIP3, and NNMT after mapping with PubMed, OMIM, MeSH, and PMC databases." (PMID 32523911, 2020). "It has been shown that CALD1 plays a key regulatory role in the growth, migration, invasion, and apoptosis of tumor cells, and enrichment of CALD1 is linked to poor metastasis and prognosis in different cancers, including gastric, bladder, and colorectal cancers." (PMID 38025524, 2023). "The poor prognosis of colorectal cancer was linked to TGF-β signaling in stromal cells, thus linking CALD1 to TGF-β signaling in the tumor stroma." (PMID 36768598, 2023). "A bioinformatics-based study showed that CALD1 was upregulated in early-onset colorectal cancer, which is a heterogenous group, most of which share a poor prognosis compared to old-age cancers." (PMID 36768598, 2023). "In conclusion, the question remains why the l-CaD protein and CALD1 gene are more expressed at the premetastatic phase of colorectal cancer." (PMID 36768598, 2023). "Enhanced expression of CALD1 imparts resistance to chemotherapeutic drug (5-FU) and radiation treatment in colorectal cancer cells." (PMID 35642021, 2022). "Accumulated studies on the CALD1 gene have shown that its alternative splicing was a pattern of colorectal cancer-specific alterations." (PMID 33397428, 2021). "On one side, CALD1 has been identified as a potential repressor of invasion into colorectal cancer cells." (PMID 29681787, 2018). "The CALD1 gene has been associated with TGF-β signaling activation, stromal invasion by malignant cells, and marked angiogenesis in the consensus molecular subtype 4 of colorectal cancer." (PMID 36768598, 2023). "A comprehensive in silico analysis using bioinformatics of the poor-prognosis subtypes of colorectal cancer in three common classification systems identified the CALD1 gene as one of the important stromal markers of poor prognosis in the Human Protein Atlas dataset." (PMID 36768598, 2023).
colon carcinoma (7 papers, 2008 to 2022). "Similar to ANXA1, also CALD1 has been shown to display opposite roles in cancer and invasion, since its expression has been associated to reduced cell invasion in colon cancer cell lines." (PMID 26657294, 2016). "In colon cancer tissues, the longest CALD1 transcript is reported to be reduced, with the increase of its shorter splicing isoform." (PMID 33563334, 2021). "In the exon array study for prostate and colon cancer, only CALD1 was in common with our validated gene list." (PMID 18474104, 2008). "The AS of CALD1, COL6A3, FN1, MAST2, LGR5 and ITGB4 were previously validated in colon cancer using RT-PCR24, while CLSTN1, AUP1, CTNND1, CALD1 and COL6A3 were shown to exhibit tumour-specific splice variants in colon, bladder and prostate cancers." (PMID 28592875, 2017). "Four genes that are involved in calcium binding or signaling were co-regulated with TAZ-AXL-CTGF in the colon cancer specimens, including FBN1, CALD1, MGP and MYL9." (PMID 23372686, 2013). "Interestingly, multiple genes involved in calcium signaling (FBN1, CALD1, MGP and MYL9) were co-overexpressed with TAZ-AXL-CTGF in colon cancer." (PMID 23372686, 2013).
breast carcinoma (5 papers, 2016 to 2025). "Though association of CALD1 to breast cancer therapy outcome has been poorly assessed so far, ANXA1 expression was previously associated to BRCA1/2 mutation carriers and prediction of high mortality risk in Her2+ patients." (PMID 26657294, 2016). "Further studies of CALD1 in breast cancer have suggested that CALD1 could be a marker for tamoxifen resistance and cancer recurrence." (PMID 41463252, 2025). "In breast cancer cells, silencing of the estrogen receptor led to CALD1 upregulation." (PMID 41463252, 2025). "In order to further confirm our findings, ANXA1 and CALD1 protein levels were assessed through IHC staining on an independent cohort of 408 FFPE tumor tissues derived from patients that received tamoxifen as first line therapy for recurrent breast cancer." (PMID 26657294, 2016). "In addition to this, CALD1 interaction with cGMP-dependent protein kinase Iβ has been shown to regulate cell invasion and migration in breast cancer cell lines." (PMID 26657294, 2016). "Our data might suggest an additional role of ANXA1 and CALD1 in disease progression after tamoxifen therapy of ER positive recurrent breast cancers." (PMID 26657294, 2016). "However, due to the low amount of tumors comprised in each category, further verification is needed to assess whether ANXA1 and CALD1 can be used in combination to effectively identify fast progressing breast carcinomas." (PMID 26657294, 2016).
endometriosis (4 papers, 2013 to 2025). The growth of functional endometrial tissue in anatomic sites outside the uterine body. "Of the 210 consensus clusters showing differential expression, 53 promoters passed Bonferroni correction, including genes (IGFBP5, OXTR CALD1) previously associated with endometriosis." (PMID 37443771, 2023). "Previous studies have indicated altered levels of the CALD1 gene (encoding the protein caldesmon) in endometriosis." (PMID 23956867, 2013). "The potential role of CALD1 in endometriosis pathogenesis in both the context of eutopic and ectopic endometrial cell types warrants further functional investigation." (PMID 37443771, 2023). "Despite the small sample number, there was evidence of differences associated with endometriosis at 210 consensus clusters, including IGFBP5, CALD1 and OXTR." (PMID 37443771, 2023). "Of particular note is the role of CALD1 (calmodulin), a much-cited gene in endometriosis research." (PMID 39858463, 2025). "Twelve consensus clusters were identified for CALD1 in endometrial stromal cells, six consensus clusters showed significantly low expression in women with endometriosis compared to women without endometriosis." (PMID 37443771, 2023).
lung carcinoma (3 papers, 2023 to 2024). "The detailed mechanism for GR-induced upregulation in PCa is not known, but interestingly previous work shows that activated GR binds to CALD1 promoter in lung cancer cells, providing a mechanism for l-CaD upregulation by GR." (PMID 37573448, 2023). "Furthermore, glucocorticoid stimulation upregulates or overexpresses CALD1 as a regulatory protein involved in actomyosin contraction and actin filament stability within lung cancer cells." (PMID 38365611, 2024).
prostate carcinoma (3 papers, 2023 to 2024). A carcinoma that arises from epithelial cells of the prostate gland. "Network analysis was performed on the intersection of 300 genes from these six datasets, and qRT-PCR validation confirmed the 3 top hub genes (TPM1, ITGB3, and CALD1) in the network are expression in prostate cancer tissues." (PMID 38778150, 2024). "In prostate cancer patients, the serum concentration of CALD1 was significantly lower than that of the general population." (PMID 38365611, 2024). "A core network consisting of 19 genes was identified, and most genes in the core network have been reported to play important roles in prostate cancer, especially TPM1, ITGB3, and CALD1." (PMID 38778150, 2024).
sarcoma (3 papers, 2021 to 2025). A usually aggressive malignant neoplasm of the soft tissue or bone. "CALD1, which encodes both h-caldesmon and l-caldesmon via alternative splicing, also emerged as a commonly activated gene in PLMSs and high-grade sarcomas." (PMID 40868997, 2025).
aneurysm (2 papers, 2009 to 2018). Bulging or ballooning in an area of an artery secondary to arterial wall weakening. "Increased expression of Acta2 and other genes encoding smooth muscle cell proteins (Cald1, Dstn), in aortas protected from aneurysm, highlight the importance of vascular smooth muscle cells in maintaining vascular integrity." (PMID 19580648, 2009). "It is reported that the expression of caldesmon 1 (CALD1) is increased in aortas, which protects from aneurysm." (PMID 29439675, 2018).
atherosclerosis (2 papers, 2021 to 2025). A disease characterized by the build-up of fatty material and calcium deposition in the arterial wall resulting in partial or complete occlusion of the arterial lumen. "We identified 12 lactylation-related genes that are more reliably associated with atherosclerosis: five upregulated genes (LSP1, IKZF1, MNDA, RCC2, and WAS) and seven downregulated genes (CSRP2, PPP1CB, CSRP1, HEXIM1, CALD1, PDLIM1, and RANBP2)." (PMID 40248193, 2025).
cardiomyopathies (2 papers, 2016 to 2017). "Some DEGs related to cytoskeleton organization (e.g. MTSS1, ACTN4 and CALD1), cardiomyopathy (e.g. ITGB5) and immune response (e.g. C1S and C1R), as well as some regulators (e.g. LEF1 and hsa-miR-33a) might play pivotal roles in the progression of DN." (PMID 27613243, 2016).
colon adenocarcinoma (2 papers, 2020 to 2023). "In silico, analysis of the TCGA colon adenocarcinoma cohort showed that the stage-specific pattern of the CALD1 gene expression was consistent with our observation and that the CALD1 gene was associated with poor overall survival of colon adenocarcinoma cases." (PMID 36768598, 2023). "In the TCGA cohort, there was also a trend of colon adenocarcinoma cases with high CALD1 expression having poor survival compared to those with low CALD1 expression." (PMID 36768598, 2023). "In silico analysis of the CALD1 gene expression showed a similar pattern in the colon adenocarcinoma cohort of the TCGA database." (PMID 36768598, 2023). "To validate our data in a separate cohort and to find out if these data could be generalized, we searched “The Cancer Genome Atlas” (TCGA) dataset (n = 275) for the CALD1 gene expression in the colon adenocarcinoma cohort." (PMID 36768598, 2023).
diabetes nephropathy (2 papers, 2021 to 2022). "Interestingly, Cald1 mRNA levels are also elevated in the glomeruli of humans with diabetic nephropathy." (PMID 34502419, 2021).
glaucoma (2 papers, 2019 to 2021). Increased pressure in the eyeball due to obstruction of the outflow of aqueous humor. "Therefore, CALD1 has been proposed for gene therapy of glaucoma." (PMID 30899261, 2019).
hepatocellular carcinoma (2 papers, 2017 to 2022). A malignant tumor that arises from hepatocytes. "Just the variants in DNAI1 and CALD1 have been reported in ExAC very rarely (heterozygote frequency < 0.01%); the DNAI1 variant was found in a hepatocellular carcinoma (COSMIC)." (PMID 29213343, 2017). "Moreover, AHSA1 promoted proliferation, metastasis, epithelium-mesenchymal transition of hepatocellular carcinoma both in vitro and in vivo by recruiting ERK1/2 and promoting the phosphorylation and inactivation of CALD1." (PMID 36230524, 2022).
leiomyosarcoma (2 papers, 2007 to 2013). An uncommon, aggressive malignant smooth muscle neoplasm, usually occurring in post-menopausal women. "Finally, we confirmed the expected overexpression of some genes: KIT and ANO1/DOG1 in GISTs, MDM2 and CDK4 in non-myxoid/round cells liposarcomas, CALD1 and tropomyosin genes (TPM1, TPM2) in leiomyosarcomas, PDGFB in DFSPs, MUC1/EMA in synovial sarcomas, and CD34 in SFTs." (PMID 23734203, 2013).
non-small cell lung carcinoma (2 papers, 2021). A group of at least three distinct histological types of lung cancer, including non-small cell squamous cell carcinoma, adenocarcinoma, and large cell carcinoma. "For example, the intracranial metastasis of non-small cell lung cancer cell is strongly correlated with the up-regulation of CALD1." (PMID 35127818, 2021).
ovarian carcinoma (2 papers, 2024). A malignant neoplasm originating from the surface ovarian epithelium. "It was found that compared with the early stage of ovarian cancer, the expression of CALD1 increased significantly in stageIII-IV." (PMID 38365611, 2024). "The impact of CALD1 on the ovarian cancer phenotype and the specific regulatory mechanisms by which XTP8 modulates CALD1 represent avenues for future research." (PMID 38717641, 2024). "The collaborative action of XTP8 and CALD1 activates the AKT/AMPK/mTOR pathway, regulating EMT to promote ovarian cancer progression." (PMID 38717641, 2024).
prostate tumor (2 papers, 2019 to 2020). "For CALD1 exon 6 skipping, the same splicing event was reported to be present in colon, bladder and prostate tumors compared to normal tissues." (PMID 32503434, 2020). "Previous publications indicate that all four of the biomarkers tested in the current work (PAK7, TARDBP, TLN1 and CALD1) are highly expressed in prostate tumor cells as compared with non-cancerous prostate tissues." (PMID 31404106, 2019).
soft tissue sarcoma (2 papers, 2021 to 2024). A malignant neoplasm arising from muscle tissue, adipose tissue, blood vessels, fibrous tissue, or other supportive tissues excluding the bones. "In conclusion, this study determined that relative RNA expression levels of TYR, CD34, and CALD1 discriminate between canine oral melanomas and soft tissue sarcomas." (PMID 34422947, 2021). "In that circumstance, RNA expression of TYR, CALD1 and CD34 has been shown to be discriminatory between spindloid oral melanoma and soft tissue sarcoma lesions [LOE 5, OEG D]." (PMID 38645640, 2024).
abdominal hernia (1 paper, 2022). "To our knowledge, this study also represents the first GWAS of hiatus hernia in which we identified eight susceptibility loci of which four loci (2p16.1 (EFEMP1), 6p22.2 (BTN2A1), 7q33 (CALD1), 11p13 (WT1) are known to correlate with abdominal hernia." (PMID 36584111, 2022).
anaplastic astrocytoma (1 paper, 2021). "Though other research has found that h-CALD1 appears to be the most specific and sensitive marker for vessel wall detection, we believe that l-CALD1 can imply abnormal microvessels in anaplastic astrocytoma and GBM." (PMID 34070840, 2021). "The findings of this study suggested that l-CALD1 could imply abnormal microvessels in anaplastic astrocytoma and GBM." (PMID 34070840, 2021).
aortic valve disease (1 paper, 2026). "Here, we present the first data indicating a role for caldesmon-1 (CALD1) in calcified aortic valve disease (CAVD) pathogenesis." (PMID 41703153, 2026).
aortic valve stenosis (1 paper, 2026). Aortic valve stenosis (AVS) is a condition characterized by narrowing of the heart's aortic valve opening. "Analysis of publicly available single-cell RNA sequencing (scRNA-seq) datasets revealed that CALD1 shows prominent upregulation in aortic valve stenosis (AS) cases when compared to normal subjects." (PMID 41703153, 2026).
astrocytoma (1 paper, 2021). "In pilocytic and diffusion astrocytoma, l-CALD1 were stained and located in microvessels with the normal vascular morphology." (PMID 34070840, 2021).
Autoimmunity (1 paper, 2019). The occurrence of an immune reaction against the organism's own cells or tissues. "Pathologic changes in CALD1 expression, incomplete protein folding or post-translational modification could induce autoimmunity to this antigen." (PMID 30899261, 2019).
brain tumors (1 paper, 2023). "This includes KIAA1549 and CALD1, which are associated with brain tumors and regulation of muscle contraction, respectively." (PMID 37664632, 2023).
breast tumor (1 paper, 2014). "Previously identified chromatin-associated lncRNAs (CARs) were predominantly downregulated in breast tumor samples, including CARs located in the protein-coding genes for CALD1, FTX, and HNRNPH1." (PMID 25264628, 2014).
carcinoma in situ (1 paper, 2024). "However, it has been reported that, in carcinoma in situ, early stage of cancer, invasive cancer and cancer metastasis, the expression of CALD1 is higher than that in normal tissues and is associated with poor tumor prognosis." (PMID 38365611, 2024).
endometrial cancer (1 paper, 2019). Primary or metastatic malignant neoplasm involving the endometrium (mucous membrane that lines the endometrial cavity). "Conversely, Hypo-O-GlcNAcylation impaired endometrial cancer cell proliferation and wound healing, and down-regulated expression of pro-EMT genes (AHNAK, CALD1, and TGFB2)." (PMID 31080560, 2019).
Hepatic failure (1 paper, 2023). "On the other hand, liver cirrhosis, fatty liver, and hepatic failure phenotypes were associated with variants in NAB1, CALD1, ZBTB16, GAN, TEMD3, and/or PRDM15 genes." (PMID 37664632, 2023).
Hernia (1 paper, 2022). "Five biologically relevant loci were discovered on individual hernia analyses to confer shared susceptibility to multiple hernia phenotypes including 1q41 (ZC3H11B), 2p16.1 (EFEMP1), 6p22.1 (MHC region), 7q33 (CALD1) and 11p13 (WT1)." (PMID 36584111, 2022). "Evidence for shared susceptibility was further provided at nine loci including 2p21 (THADA), 3p14.3 (ERC2), 3p13 FOXP1, 4q34.1 (HAND-AS1), 5p15.33 (CEP72), 7p15.2 (LOC646588), 7q33 (CALD1) and 9q22.31 (BARX1) of which eight were previously discovered on individual hernia GWAS analyses." (PMID 36584111, 2022).
liver cancer (1 paper, 2024). An epithelial or non-epithelial malignant neoplasm that arises from the liver. "CALD1 acts as a downstream target of AHSA1, promoting proliferation and EMT in liver cancer." (PMID 38717641, 2024).
liver fibrosis (1 paper, 2022). "Cald1 is an actin- and calmodulin-binding molecule crucial for the regulation of smooth-muscle and non-muscle cell contraction, which was reported to be upregulated in liver fibrosis." (PMID 35719864, 2022).
lymph node metastasis (1 paper, 2021). "We also found a significant association between patients with lymph node metastasis and overexpression of BMP7 (47.4%, P=0.005), CALD1 (42.1%, P=0.020), CDH1 (52.6%, P=0.001), COL3A1 (42.1%, P=0.020), EGFR (47.4%, P=0.005), ERBB3 (57.9%, P=0.000), PLEK2 (47.4%, P=0.024), and TCF4 (52.6%, P=0.001)." (PMID 34527572, 2021).
malignant glioma (1 paper, 2023). A grade III or grade IV glioma arising from the central nervous system. "By performing differential expression analysis on our malignant glioma samples, we identified four DEGs, CD74, HES1, CALD1, and HEBP2, significantly upregulated in the AQP4 high expression group." (PMID 36599974, 2023).
medulloblastoma (1 paper, 2018). A malignant, invasive embryonal neoplasm arising from the cerebellum. "The protein expression level of CALD1 isoforms in medulloblastoma subgroups is confirmed at the epigenetic (H3K27Ac Chip-seq) and mRNA level." (PMID 29880060, 2018).
melanocytic neoplasm (1 paper, 2021). "The proteins encoded by CD34 and CALD1 have been shown to be expressed in various types of STS in dogs, but not melanocytic neoplasms." (PMID 34422947, 2021).
metastatic cancer (1 paper, 2024). A carcinoma which has spread from the original site of growth to another anatomic site. "All these results support the conclusions of the literatures above, which is the high expression of CALD1 is associated with metastatic cancer cells." (PMID 38365611, 2024).
mucinous cystadenocarcinoma (1 paper, 2024). An invasive adenocarcinoma characterized by cystic changes and the presence of malignant glandular cells which contain intracytoplasmic mucin. "IHC analysis from the HPA database revealed that CALD1 was highly expressed in normal ovarian cells and exhibited strong or moderate expression levels across various types of ovarian malignancies including serous cystadenocarcinoma, mucinous cystadenocarcinoma and endometroid carcinoma of ovary." (PMID 38365611, 2024).
Nephropathy (1 paper, 2016). A nonspecific term referring to disease or damage of the kidneys. "A previous study has shown that CALD1 is over-expressed in fibroblasts from the diabetic patients with nephropathy, compared with those from the controls." (PMID 27613243, 2016).